GPX4 (glutathione peroxidase 4)
Diseases named in the same sentence as GPX4 in open-access papers (continued):
Sharing a sentence is not in itself a finding about the gene and the disease.
ZIKV infection (1 paper, 2018). "ZIKV infection increased GPx4 expression in sperm on 3 dpi, presumably due to the altered cellular response associated with viral replication (Mock vs. ZIKV)." (PMID 29447264, 2018). "Moreover, the expression of the scavenging enzyme GPx4, the most highly expressed GPx isoform that supports the middle piece structure of sperm, was also affected by ZIKV infection." (PMID 29447264, 2018).
Zinc deficiency (1 paper, 2025). A deficiency of the essential metal Zinc; an essential cofactor for many enzymes. "Zinc deficiency impairs GPX4 activity indirectly, rendering neurons more susceptible to ferroptotic stress, while zinc overload promotes lipid peroxidation and ferroptosis-like phenotypes in dopaminergic cell models." (PMID 40507121, 2025).
tumor (988 papers, 2011 to 2026). "GPX4-deficient tumor cells evade ferroptosis by upregulating the expression of DGAT1/2 to promote the synthesis of triacylglycerol (TAG) and oxidized TAG (oxTAG) and the formation of lipid droplets in cells." (PMID 41259048, 2026). "A recent study demonstrates that sustained GPX4 blockade via sophisticated lipidic nanoplatforms simultaneously triggers robust ferroptosis and remodels the tumor immune microenvironment; however, the underlying synergistic mechanisms remain poorly elucidated." (PMID 42244975, 2026). "In tumor cells with low expression levels of GPX4, DHODH enhances susceptibility to ferroptosis by utilizing CoQ10 to eliminate intra-mitochondrial ROS." (PMID 40248093, 2025). "Conversely, BRCA1 deficiency leads to increased GPX4 levels, inhibiting ferroptosis and promoting tumor growth." (PMID 40539051, 2025). "FSP1 can prevent ferroptosis even in GPX4‐deficient cells and contributes to resistance in certain tumor types." (PMID 40900810, 2025). "In recent years, several studies have demonstrated that increased GPX4 expression is linked to tumor cell proliferation, growth, migration, and differentiation." (PMID 40969276, 2025). "Researchers identified genes in tumor cells capable of compensating for the deficiency of GPX4, a key enzyme in ferroptosis, through expression cloning." (PMID 40735482, 2025). "The high level of GPX4 expression is linked to the development of chemical resistance in a range of malignancies as well as the prognosis of tumor patients." (PMID 40969276, 2025). "Further animal experiments showed that intraperitoneal injection of kynurenine in mice reduced the tumor-suppressive effects and survival benefits associated with GPX4 knockdown in GC cells." (PMID 40365295, 2025). "Studies have shown that high expression of GPX4 in lung adenocarcinoma (LUAD) is linked to tumor aggressiveness and drug resistance, with its expression level negatively correlated with patient survival." (PMID 39917300, 2025). "For example, although some polyphenols exhibit potent GPX4 inhibitory activity in vitro, they are susceptible to rapid metabolism or have difficulty penetrating tumor tissues in vivo." (PMID 40559667, 2025). "Tumor cells with a high burden of RAS mutations often exhibit sensitivity to GPX4‐mediated ferroptosis." (PMID 40599237, 2025). "On the basis of in vitro mechanisms studies, molecules associated with MCMSFT-mediated ferroptosis, including ROS, GPX4, and ferritin, were examined in tumor sections by fluorescence or immunofluorescence staining." (PMID 40367177, 2025). "The effectiveness of the combined treatment was further demonstrated by xenograft studies, evidencing a significant decrease in tumor weight and volume associated with an enhanced expression of GPX4 and SLC7A11 in response to TAZ." (PMID 40229247, 2025). "An increase in GPX4 expression in tumor cells can make them more susceptible to ferroptosis-inducing agents." (PMID 39987248, 2025). "The SLC7A11/GPX4 pathway is classic for regulating ferroptosis and is closely associated with tumor progression." (PMID 41516285, 2025). "Our studies confirmed that GPx4 is significantly upregulated as GC progresses and is closely linked to tumor metastasis and overall survival in GC patients." (PMID 39908861, 2025). "This phenomenon suggests that the functional status of GPX4 is a key molecular switch that determines the susceptibility of tumor cells to ferroptosis." (PMID 40559667, 2025). "Beyond the GPx4 pathway, it has been established that certain tumor cells can survive and proliferate despite GPx4 deficiency, owing to compensatory non-GPx4-dependent regulatory pathways." (PMID 40092979, 2025). "This combination downregulates GPX4, induces immunogenic ferroptosis, and triggers the release of damage-associated molecular patterns (DAMPs), which activate the NF-κB pathway in tumor-associated macrophages." (PMID 40919170, 2025).
tumor (continued). "This study revealed that GPX4 in GC cells affected tumor growth via regulating tumor immune microenvironment, especially in tumor associated macrophage (TAM) polarization." (PMID 40365295, 2025). "ov-TCF3 led to a notable rise in tumor volume, weight, and levels of TMBIM6 and GPX4, while causing a significant decrease in tumor Ca2+ concentration." (PMID 40610429, 2025). "Glutathione peroxidase 4 (GPX4), a core regulator of ferroptosis, directly triggers irreversible tumor cell death upon loss of its activity, providing a theoretical foundation for ferroptosis-based cancer therapies." (PMID 40862825, 2025). "On the other hand, acute cell death caused by GPX4 depletion can eliminate tumor cells, release DAMPs, and activate antitumor immunity." (PMID 38515187, 2024). "It was found that M1 phenotype of tumor-associated macrophages (TAMs) is more resistant to ferroptosis caused by GPX4 deletion than M2 phenotype." (PMID 38475936, 2024). "Increased expression of GPX4 is associated with large invasion depth, advanced tumor stage, and high grade of tumors in patients with oral squamous cell carcinoma." (PMID 38778030, 2024). "GPX4, a key regulator of ferroptosis, has higher expression levels in tumor tissues compared with normal tissues, with the higher GPX4 expression levels associated with shorter overall survival." (PMID 39664583, 2024). "The overexpression of CX3CL1, a chemokine associated with the immune infiltration of tumor cells, leads to the downregulation of GPX4, thereby inhibiting the GSH/GPX4 axis." (PMID 39399506, 2024). "This approach aids in predicting the susceptibility of tumor cells to ferroptosis-inducing drugs targeting GPX4, such as altretamine and sorafenib." (PMID 38844964, 2024). "DT anti-tumor mechanism is associated with ferroptosis induced by down-regulating GPX4 protein expression." (PMID 38738174, 2024). "To investigate further, we used CD8-cre mice to achieve CD8+ T cell–specific GPX4 cKO (CD8-cre+gpx4fl/fl), revealing sufficient suppression of tumor growth by host GPX4-deficient CD8+ T cells." (PMID 38441967, 2024). "The deficiency of GPX4 in regulatory T cells (Tregs) leads to the occurrence of ferroptosis and promotes the production of IL-1β, thereby increasing anti-tumor immunity." (PMID 38200525, 2024). "GPX4 deficiency in T cells significantly accelerated the tumor growth accompanied with diminished intratumoral T cell accumulation." (PMID 38441967, 2024). "Subsequently, the intracellular PLs‐AA was oxidized to cytotoxic PL‐AA‐OOH by lipoxygenase (LOXs) which was synergized with FIN56‐mediated GPX4 loss for effective tumor ferroptosis." (PMID 37984863, 2024). "Tumor-associated macrophages (TAMs) that exhibit an M2-like phenotype and suppress antitumor immunity are more vulnerable to ferroptosis induced by GPX4 inhibition than M1-like TAMs, which promote antitumor immunity." (PMID 38322268, 2024). "TSPO, which was directly linked to GPX4-driven ferroptosis in the murine model, was highly upregulated in quiescent tumor cell populations." (PMID 39192032, 2024). "It is reported that a loss of GPX4 function results in tumor cell ferroptosis and prevents tumor relapse." (PMID 38399303, 2024). "GPX4 deficiency in T cells significantly accelerated tumor growth and mitigated the accumulation and function of CD8+ T cells accompanying decreased infiltration of total CD4+ T cells and CD4+Foxp3+ regulatory T cells in comparison with the control mice." (PMID 38441967, 2024). "CHAC1, in addition to NOX4 and GPX4, is considered to be a hallmark of ferroptosis and has been reported to be involved in tumor cell death via the induction of ferroptosis." (PMID 37371096, 2023).
tumor (continued). "Ribosomes are frequently upregulated in tumor cells, and GPX4 is a selenoprotein whose synthesis is associated with the large subunit of ribosomes." (PMID 38086802, 2023). "On the other hand, some immunosuppressive immune cells, including M2 tumor-associated macrophages and T regulatory cells, also need FRGs, such as Glutathione peroxidase 4 (GPX4), to suppress ferroptosis and maintain cell activation." (PMID 37940859, 2023). "Wang et al12 showed that the mutation rate of GPX4 gene in GC was low (only 2.1%) by RNA sequencing of GC tissues from multiple tumor gene databases." (PMID 37768308, 2023). "Previous studies have indicated that GPX4 inactivation and ferroptosis caused by iron accumulation are important factors in tumor suppression." (PMID 37488128, 2023). "For late infection and virus-induced diseases, especially virus-associated tumor diseases, GPX4 is often upregulated to resist the cytocidal effect of host or drugs on tumor cells." (PMID 38140616, 2023). "According to the mechanism of ferroptosis, in addition to Fe, other metal‐based nanomaterials capable of causing GSH depletion and GPX4 inactivation can be utilized for tumor ferroptosis therapy." (PMID 37933288, 2023). "Inhibition of TRIM26 phosphorylation causes a reduction in GPX4 K63-linked polyubiquitination and diminishes GPX4 protein levels in tumor cells." (PMID 37872147, 2023). "It has been shown that iFSP1, an inhibitor of FSP1, promotes ferroptosis in GPX4-deficient tumor cells." (PMID 37408372, 2023). "Our study elucidates the underlying mechanism of ferroptosis in tumor cells, providing a promising novel approach for future therapies by targeting the NeuroD1/GPX4 axis." (PMID 38134213, 2023). "It has been shown that Gpx4 deficiency-induced ferroptosis in Treg cells within tumors enhances antitumor immunity and promotes tumor regression." (PMID 36845720, 2023). "Our results showed that PSMD14 depletion can inhibit BC tumor cell growth by decreasing GPX4, and high expression of PSMD14 is an independent risk factor for worse DFS in BC." (PMID 36632137, 2023). "Ferroptosis can serve as the metabolic vulnerability of tumor-specific CD8 + T cells, while GPX4-deficient T cells render high sensitivity to ferroptosis, consequently being unable to exert an ant i-tumor effect." (PMID 36335094, 2022). "More critically, increasing evidence has illustrated that GPX4 is associated with the regulation of tumor immune responses." (PMID 35620733, 2022). "These microRNAs directly bound to the 3′-UTR of GPX4 mRNA and inhibited its expression, causing ROS accumulation in tumor cells and acting as tumor suppressor genes." (PMID 36310600, 2022). "GPX4 was found to be upregulated in several tumor tissues and inversely associated with patient survival based on pan-cancer analysis using The Cancer Genome Atlas (TCGA)." (PMID 35620733, 2022). "In peri-tumor-associated inflammatory cells, GPX4 deletion in myeloid cells mediated an increase in ROS production, which was accompanied by secretion of excess H2O2, transforming intestinal epithelial cells (IECs) by triggering DNA mutations." (PMID 36158661, 2022). "Employing the murine tumor vaccination model, loss of Gpx4 neutralized the immunosuppressive effects of PTENα and remarkably increased the effectiveness of tumor vaccination." (PMID 34446716, 2021). "A previous study reported that ferroptosis regulators like GPX4 are associated with tumor progression and tumor sensitivity to treatments, such as hepatocellular carcinoma, renal cell carcinoma, breast cancer, prostate cancer, and bladder carcinoma." (PMID 35126346, 2021). "As a key regulator of ferroptosis, the inhibition of GPX4 makes drug-resistant tumor cells susceptible to ferroptosis, yet some tumor cells develop resistance mechanisms independent of ferroptosis." (PMID 35111195, 2021).
tumor (continued). "GPX4 and tumors are also linked by ferroptosis; although GPX4 inhibitors can induce ferroptosis in tumor cells, different tumor cells respond differently to GPX4 inhibitors." (PMID 34007403, 2021). "The cystine/glutamate antiporter inhibitors erastin and sulfasalazine can inhibit the uptake of cystine, cause glutathione peroxidase 4 (GPX4) inactivation and lead to increased accumulation of lipid peroxidation in tumor cells." (PMID 31935835, 2020). "Loss of GPX-4 function results in selective ferroptotic cell death and prevents tumor relapse in mice." (PMID 30186549, 2018). "High GPx4 expression was also associated with a shift from M2 toward M1 macrophages characteristic for tumor suppression." (PMID 29515790, 2018). "Collectively, our results establish TGM2-mediated GPX4 serotonylation as a key mechanism driving GC progression through ferroptosis resistance, highlighting its potential as both a diagnostic biomarker and a therapeutic target within the neural-tumor axis." (PMID 42049702, 2026). "Hypoxia-mediated downregulation of GPX4 in tumor PMN-MDSC renders it susceptible to ferroptosis." (PMID 41154692, 2025). "Furthermore, analysis using the TISIDB database revealed that expression of GPX4 was associated with tumor grade in HNSC, KIRC, LGG, LIHC, STAD, and UCEC." (PMID 41142608, 2025). "The article reviews the roles of selenium and related selenoproteins in immune regulation, analyzes their metabolic processes in solid tumors, and particularly emphasizes the association between GPX4, ferroptosis, and autophagy, offering a theoretical basis for tumor research and treatment." (PMID 41323827, 2025). "To investigate the relationship between the FX-mediated suppression of tumor development and ferroptosis, we conducted an immunohistochemistry (IHC) analysis to assess the expression of vital ferroptosis-associated targets, including SLC7A11 and GPX4 in tumor tissues." (PMID 40137309, 2025). "Notably, both GLS1 and GPX4 exhibit high expression levels in tumour tissues, which are associated with an unfavourable prognosis." (PMID 40259435, 2025). "Consequently, the definitive causal role of STMN1/PRDX1 in regulating LDHA/GPX4 and driving tumor progression in a physiological context remains to be established." (PMID 41403955, 2025). "Based on our experimental evidence, we propose a mechanistic framework wherein USP5 enhances GPX4 stability by suppressing its ubiquitination-mediated degradation, ultimately diminishing tumor cell susceptibility to ferroptosis and facilitating oncogenic progression." (PMID 40136465, 2025). "In such a situation, the ablation of GPx4 has been demonstrated to render tumor cells more susceptible to ferroptosis-eliciting agents, suggesting that GPx4 may emerge as a promising target for the development of novel therapeutic interventions." (PMID 39839762, 2024). "Interestingly, depletion of TMEM173/STING protects against GPx4-depletion-induced neoplastic progression and reduces tumor-associated macrophages." (PMID 39594547, 2024). "Consequently, the loss of GPX4 presents a potential avenue for selectively eliminating therapy-resistant tumor cells and averting relapse." (PMID 38561331, 2024). "GPX4 maintains intracellular redox homeostasis by inhibiting lipid peroxidation and shielding cells from ferroptosis, and has been found to be closely associated with tumor progression in previous studies." (PMID 38369484, 2024). "Research has shown that GPX4 dysfunction is associated with tumor cell resistance." (PMID 39045454, 2024). "Notably, we identified Apoptosis-Inducing Factor Mitochondria Associated 2 (AIFM2) and Glutathione Peroxidase 4 (GPX4), pivotal regulators of tumor ferroptosis, as direct targets of miR-6805." (PMID 38244593, 2024). "Silencing of PSMD14 suppressed tumor cell growth, and was associated with down-regulation of GPX4." (PMID 36632137, 2023).